TNF (tumor necrosis factor)
Diseases named in the same sentence as TNF in open-access papers (continued):
Sharing a sentence is not in itself a finding about the gene and the disease.
tumor (continued). "TUBB2B regulated the expression of TNF-a, IL-6, and PD-1/PD-L1 through the inhibit tumor invasion gene PER1." (PMID 37719786, 2023). "These cells bind IgE with high affinity, producing TNF-α and granulocyte macrophage colony-stimulating factor (GM-CSF) in the tumour microenvironment." (PMID 37488447, 2023). "Intrinsically, NK cells require secretion of interferon gamma (IFNγ), tumor necrosis factor alpha (TNFα) and granzyme B for anti-tumor response." (PMID 38193082, 2023). "IFNγ and TNFα production triggered in NK cells against these tumor cells was significantly lower than that induced by TriKE in response to NCI-H460, for all disease stages (I-IVB) and timepoints (before treatment, after treatment or at progression)." (PMID 36911670, 2023). "CD8+ cytotoxic T lymphocytes are the main subgroup of CD8+ T cells, which can kill tumor cells by secreting effectors such as perforin, granzymes, and TNF." (PMID 36983615, 2023). "The tumour cells infiltrated in the inflammatory mediators, and the inflammatory cells collaborated with the pro-inflammatory cytokines (such as interleukins, TNF-α), growth factors and chemokines to create the inflammatory microenvironment." (PMID 37742025, 2023). "CD103+ DCs from tumor-draining lymph nodes express increased levels of PD-L1, and blockade of PD-L1 and PD-1 mitigates DC dysfunction in terms of TNF-α, IL-12, and IL-1β production and enhances T-cell-stimulatory capacity." (PMID 36949244, 2023). "It has also been reported that macrophages can regulate the tumor microenvironment via producing iNOS, NO, or other pro-inflammatory cytokines (e.g., TNF-α and IL-6)." (PMID 36827169, 2023). "CD4+ T cells also produce cytokines, such as IFN-γ and TNF-α, which have direct anti-tumor effects and can promote the recruitment and activation of other immune cells." (PMID 37509488, 2023). "To test induction of mICAM-1 expression and sICAM-1 release, we stimulated various tumor cell lines with TNF-α, IFN-γ or the combination of both." (PMID 37732732, 2023). "Consistent with the literature, we observed that UA downregulated elevated IL-6, IL-1β, and TNF-α levels in the serum of LLC tumor-bearing mice and inhibited elevated phosphorylation of NF-κB and STAT3." (PMID 37190306, 2023). "It was also pointed out that cathelicidin reduced the tumor growth and regulated necrosis of cancer cells by releasing tumor necrosis factor-alpha (TNF-α) and granules enzymes." (PMID 38298540, 2023). "Additional mechanisms explained the IL-32 anti-tumor activities through its ability to modulate other cytokines and immune cells including TNF-α." (PMID 36845147, 2023). "M1 neutrophils enhance the body's anti-tumor function and improve host immunity by producing the tumor necrosis factor-α (TNF-α), etc., and reducing arginase level." (PMID 36855112, 2023). "IFNγ and TNF-α are pleiotropic cytokines with both anti- and pro-tumoral effects, depending on context and elements in the tumour microenvironment (Waters, Pober, and Bradley, 2013a; Waters, Pober, and Bradley, 2013b; Gocher, Workman, and Vignali, 2022)." (PMID 37346794, 2023). "We observed that CD4+ and CD8+ T cell populations both exhibited increased secretion of interferon (IFN)-γ, tumor necrosis factor (TNF)-α, and interleukin (IL)-2, which are associated with anti-tumor activities." (PMID 36915911, 2023). "VEGF, PlGF, transforming growth factor β (TGF-β), tumor necrosis factor α (TNF-α), and G-CSF are some of the most important factors, which have been described to be secreted by the primary tumor and to affect ECs in secondary organs." (PMID 37222464, 2023). "Through the analysis of cell communication, we described the interactions between different B cells and tumor-infiltrating T cells, highlighting the potential role of receptor-ligand pairs formed by members of the TNF/TNFR family." (PMID 38149239, 2023). "TNF-α also promoted tumor invasion and metastasis by stimulating matrix metalloproteinase-9 secretion." (PMID 37068081, 2023).
tumor (continued). "According to evidence, the MacTrigger accelerated the release of TNF-α, natural killer cells, and CD8+T cells, causing efficient effective anti-tumor effects." (PMID 37509382, 2023). "A study showed that the expression and activation of MMPs are mediated through TNF-α and IL-1 secreted by tumor cells, and IL-17A secreted from the microenvironment plays a role on the regulation of different MMPs." (PMID 36993955, 2023). "These CD8+ T cells, in turn, directly facilitate tumor death and produce TNF-α and IFN-γ to further activate eosinophils, thus creating a positive feedback loop to promote their anti-tumor activity." (PMID 38137547, 2023). "As typical cytotoxic CD8+ T cells, Tc1 cells produce perforin, granzyme B, IFN-γ, and TNF-α, which enable them to eliminate tumor and infected cells." (PMID 37907738, 2023). "In B16F10 tumor-bearing mice, GRo significantly inhibited tumor growth, LPS-induced lung damage, and TNF, IL-6, and IL-1 transcript levels in tumor tissues." (PMID 38139116, 2023). "Stimulated T cells cocultured with tumor cells showed increased TNFα and IFNγ expression on both cell types, whereas recombinant VISTA protein reversed the stimulation effect, and reduced TNFα and IFNγ expression on both cell populations." (PMID 37190254, 2023). "TNF‐α is mainly secreted by macrophages and other tumour‐infiltrating immune cells, such as cytotoxic lymphocytes and natural killer (NK) cells." (PMID 37712124, 2023). "HNSCC cells were made more susceptible to radiation- and TNFα-mediated cell death by b-AP15 in vitro and in tumor xenograft models." (PMID 37658402, 2023). "Both NO and tumor TNF-α production significantly decreased after PRP and PRP + rhein treatments at 24 and 48 h." (PMID 37629580, 2023). "On the other hand, MCs represent the only cell type able to store preformed TNF-α in their granules and, upon degranulation, can also exhibit anti-tumor activity through direct tumor cell cytotoxicity mediated by TNF-α and reactive oxygen species." (PMID 36766801, 2023). "Gene expression and pathway analysis showed that tumor CM activated a number of pathways in macrophages, such as the tumor necrosis factor pathway (TNF), PI3K-Akt pathway and the VEGF signaling pathway." (PMID 37005447, 2023). "TNF-α upregulation due to S. typhimurium tumor colonization increases permeability of tumoral blood vessels, and can cause hemorrhage, enhancing the influx of immune cells and increasing the anti-tumor effects." (PMID 37514190, 2023). "On the other hand, TNF-α responsible for programmed cell death activation exerted promising anti-tumor effects in several experiments." (PMID 36839658, 2023). "The intratumour and serum levels of IL12p70, IFN-γ and TNF-α in tumour-bearing mice treated with the hydrogel microsphere vaccine were significantly higher than those in mice treated with counterpart’s hydrogel microspheres." (PMID 37433774, 2023). "More importantly, DAC had a synergistic effect with anti-PD1 antibody, promoting to a further Tpex expansion and cytokine production (IFN-γ, TNF) of CD8+ TILs in several mouse tumor models." (PMID 37398660, 2023). "The expression of all six FRGs was significantly different (p < 0.05), with FTH1, FTL, and PCBP1 being overexpressed in the tumor group and ZFP36, NCOA4, and TNF expressed less in the tumor group." (PMID 37555866, 2023). "In vitro, human platelet-derived serotonin inhibited TNFα production in stimulated monocytes and macrophages primed for anti-inflammatory signaling, and platelets downregulated TNFα production, abrogating the capacity of macrophages to kill tumor cells." (PMID 38116017, 2023). "TNF is involved in both the progression of tumors and their resistance to immunotherapies, despite its function being to prevent tumor growth." (PMID 38139369, 2023). "CAR T therapy targeting this molecule on tumor cells causes tumor cell death and increases expression of IFN gamma and TNF alpha in culture supernatant." (PMID 36900205, 2023).
tumor (continued). "TNF-α is a cytokine produced by macrophages or activated monocytes and plays a significant role in inflammatory response and tumor angiogenesis." (PMID 36647454, 2023). "The reports claim that TNF can also reduce tumor vasculature, which is another mechanism for reducing cancer growth." (PMID 37046608, 2023). "The results revealed marked localization of the RGD4C.TPA.TNFα particles within the tumor tissue, and were detected both in the tumor vasculature and tumor cells." (PMID 37331004, 2023). "This is consistent with a paradigm where small tumors, or tumor cells in vitro, occupy a state devoid of TNF-α." (PMID 37043573, 2023). "Once transformed, cancer cells can release EVs that contain pro-inflammatory factors, such IL-6 and TNF-α, which can activate signaling pathways in stromal cells and promote their migration to the tumor site." (PMID 38052753, 2023). "The supernatant levels of IL‐2 and tumor necrosis factor‐α (TNF‐α) were significantly increased in OT‐I T cells cocultured with RA‐pretreated tumor cells." (PMID 36876644, 2023). "Even at a lower concentration (10 ng/mL), TNF-α induced tumor cell death; however, cell death was increased further at a higher TNF-α concentration (50 ng/mL)." (PMID 37012245, 2023). "Regarding the mechanism by which TNFα influences tumor growth, it is known that in CRC, one of the receptors of TNFα, namely TNFR2, regulates Ki67 expression, affecting fibroblast-associated proteins and αSMA, thereby increasing cell growth and migration." (PMID 36996146, 2023). "Together, these data demonstrate that tumor presence activates an inflammatory gene program within splenic HSPCs to express TNFα." (PMID 37134077, 2023). "In this regard, it has been recently reported that “iron-retaining” M1 TAMs, showing a pro-inflammatory M1-like phenotype, induce tumor cell death and through the generation of ROS and pro-inflammatory cytokines (TNFα and IL-6)." (PMID 37377735, 2023). "In order to be further polarized to M1 macrophages, the tumor-resisting macrophages that can secret TNF-α, THP-1 cells are always treated with IFN-γ or LPS after incubating with PMA." (PMID 37432179, 2023). "TNFα production by effector T cells has also been shown to lead to tumor cell death, particularly in tumors that are sensitized to extrinsic death pathways." (PMID 37461742, 2023). "The catabolic effect of TNF-α was evidenced in a murine model, where tumor-bearing mice displayed substantially higher levels of TNF-α, atrogin-1, and muscle ring finger protein 1 (MuRF1) compared to healthy cohorts." (PMID 37755304, 2023). "Specifically, they induce immunosuppression by upregulating pro-inflammatory cytokines such as IL-6 and TNF-α in lymph nodes, inhibiting tumor immune responses." (PMID 38087360, 2023). "A number of TNF fusion proteins, capable of a preferential localization at the tumor site, are currently being investigated at the clinical level." (PMID 37092450, 2023). "TNFα was also known to permeabilize the tumor vasculature when used in the form of isolated limb perfusion through downregulation of VE‐cadherin expression." (PMID 37331004, 2023). "M1 macrophages can generate anti‐inflammatory molecules such as TNF‐α, IL‐23, and iNOS, by triggering inflammatory responses and exerting anti‐tumor effects." (PMID 37347147, 2023). "Our discovery of high levels of the pro-inflammatory cytokines TNFα, IL-1β, and IL-6 led us to test if these cytokines aided in tumor destruction or promotion." (PMID 37461742, 2023). "IFN-γ-, lipopolysaccharide-, IL-1β-, TNF-, and/or GM-CSF-activated M1-like macrophages recognize and kill tumor cells via phagocytosis and the release of proinflammatory factors that stimulate the immune system." (PMID 37568713, 2023).
tumor (continued). "In the context of cancer cachexia, TNF-α serves as a proinflammatory cytokine and mediator of tumor-induced adipose and skeletal muscle wasting." (PMID 37755304, 2023). "TIGIT blockade upregulated multiple gene sets related to NK cell anti-tumor responses, including inflammatory response-related genes, TNFα signaling via NFкB, and IFNγ response-related gene sets." (PMID 37345049, 2023). "Collectively, hPSC-derived CAR-neutrophils, particularly CD3ζ-bearing CAR-neutrophils, presented enhanced anti-tumor cytotoxicity and produced more ROS and TNF-α in vitro, highlighting their potential in targeted immunotherapy." (PMID 37080958, 2023). "Inflammatory cells, such as macrophages, neutrophils, and lymphocytes, infiltrate the tumor site and secrete pro-inflammatory cytokines, including interleukins (ILs) and tumor necrosis factor-alpha (TNF-α)." (PMID 38002286, 2023). "The anti-tumor activity of the NSP was confirmed by investigating its effect on the expression of inflammatory cytokines (TNF-α, iNOS, and TGF-1β)." (PMID 36850982, 2023). "In vitro experimental data show that M2‐TAMs promote tumor development by secreting various cytokines, such as tumor necrosis factor‐α (TNF‐α), ICAM‐1, and IL‐6, and regulating the EMT of cancer cells, thereby coordinating the immune microenvironment of iCCA." (PMID 37688511, 2023). "The most basic physiological difference between normal and tumor tissue is that many chemokines and cytokines are induced by hypoxia such as TNF-α, InterLeukin 6, and InterLeukin-1 α and β." (PMID 37298889, 2023). "TNF can be an endogenous tumor promoter because TNF stimulates tumor growth, proliferation, invasion, metastasis, and angiogenesis." (PMID 37987366, 2023). "These CD4+ subsets have autologous tumor cell killing abilities (as they secrete TNF-α and IFN-γ) ex vivo." (PMID 38328405, 2023). "The present process by which cytotoxic T lymphocytes (CTLs) eliminate tumor cells involves the secretion of various mediators and cytokines, including perforin, granzyme, and tumor necrosis factor (TNF)." (PMID 37950153, 2023). "TNF-α is a proinflammatory cytokine that regulates multiple aspects of tumor biology from initiation to progression." (PMID 38201482, 2023). "The study exposed a previously unrecognized paradox where inhibiting Cxcl1-CXCR2 engagement invigorates T-cell activation while dampening tumor-wide TNF signaling, predominantly through disruption of MDSC-restricted TNF." (PMID 37455286, 2023). "Our data also indicated that Iso2 and its downstream effects on TNF-α and T cells are required as part of the immunosuppressive effects of Iso1, and in Iso2Neg tumors, Iso1 somehow plays tumor suppressive roles." (PMID 37047287, 2023). "Significantly higher cytotoxicity, better CAR-T expansion, enhanced IFN-γ and TNF-α secretion were observed when conventional HER2 CAR-T cells were co-culture with FaDu_IL12 compared to with FaDu tumor cells." (PMID 36855120, 2023). "Third, the excessive secretion of INF-γ, TNF-α, interleukin and other pro-inflammatory cytokines in tumor microenvironment can induce the expression of PD-L1 in tumor cells through different signaling pathways and promote immune escape." (PMID 37426654, 2023). "Functionally, M1 (F4/80+CD11b+CD86+) can kill tumor cells by expressing inducible nitric oxide synthase (iNOS), reactive oxygen species (ROS), and cytokines such as IL-1β, tumor necrosis factor-alpha (TNF-α), IL-12 and IFN-γ." (PMID 37415162, 2023). "TNF-α is an inflammatory cytokine produced by activated macrophages, tumor cells, and inflammatory cells in the tumor microenvironment." (PMID 37373957, 2023). "Migration of innate immune cells including macrophages, dendritic cells, and neutrophils are enhanced by expression of pro-inflammatory cytokines such as TNF-α, IL-1β, and IL-18 to result in overall tumor regression." (PMID 37514190, 2023).
tumor (continued). "This was supported by our functional RNA analysis of the tumour tissue from ever smokers, whereby these patients significantly over-expressed pro-inflammatory genes involved in Nf-ĸB signalling, in particular TNFα and IL-1β." (PMID 37398676, 2023). "In mice bearing the H22 tumor, chiisanoside (120 mg/kg and 240 mg/kg) effectively suppresses tumor growth while upregulating the expression of cytokines such as IL-2, TNF-α, and IFN-γ." (PMID 37764339, 2023). "Another potential target is pro-inflammatory cytokines and chemokines, such as IL-6, IL-8, IL-1β, and TNF-α, which contribute to the promotion of tumor growth, angiogenesis, and metastasis." (PMID 37760801, 2023). "In this model, tumor microenvironment cells in turn secrete soluble mediators, such as IL-6, TNF-α and VEGF to promote tumor growth." (PMID 37213270, 2023). "Mechanistically, circUHRF1 inhibits NK cell–derived IFN-γ and tumor necrosis factor (TNF)-α secretion and decreases the proportion and tumor infiltration of NK cells by regulating the miR-449c-5p–TIM-3 axis." (PMID 36797245, 2023). "Intravenous administration of targeted RGD4C.TPA.TNFα to tumor‐bearing mice resulted in selective expression of TNFα and subsequent apoptosis and destruction of tumors." (PMID 37331004, 2023). "Tumor cells attract the macrophage cells in metastatic sites by releasing VEGF, CSF-1, TGF-β, and TNF-α, and these macrophages increase the tumor invasion by remodeling collagen fibers." (PMID 38017494, 2023). "Compared to the separate administration of BsAbs and T cells, using BsAb-armed T cells, known as EATs, led to reduced tumor necrosis factor-alpha (TNF-α) release, quicker tumor infiltration, and strong antitumor responses." (PMID 38111570, 2023). "T-cells obtained from mice that were vaccinated displayed tumor-specific cytotoxicity, as shown by enhanced tumor cell killing in co-culture experiments, accompanied by increased levels of Granzyme B, TNF-α, IFN-γ, and CD107a in T-cells." (PMID 37434263, 2023). "On the other hand, TNF has unique vasoactive functions, altering the blood flow and permeability of vessels, which favors the fast extravasation and tumor uptake of other drugs." (PMID 37092450, 2023). "Since human TNF-α is inflammatory and has possible tumor-promoting activity, we studied the initiating activity of human TNF-α as well." (PMID 37097392, 2023). "TNF probably stimulates T-regs and MDSCs during chronic inflammation, helping in immune evasion and tumor growth." (PMID 38139369, 2023). "In the anti-TNFα mAb group, a macroscopic reduction in tumor size was observed compared with that in the control group, along with a significant reduction in tumor weight and volume." (PMID 36996146, 2023). "In the present work, we described that TNFα inhibits mammary preadipocyte cell differentiation and promotes an inflammatory phenotype which mimics the tumor environment and malignant characteristics through an increase in mtROS production." (PMID 37107188, 2023). "TNFα is often present in large quantities in tumours, and cancer cells frequently acquire resistance to this cytokine." (PMID 36900285, 2023). "In this context, our data demonstrated that DMF significantly reduced TNFα expression in a dose-dependent manner, thus suggesting a protective role in reducing tumor migration." (PMID 36769105, 2023). "Local ULCA injection did not, however, increase levels of inflammatory cytokines IL-6 and tumor necrosis factor–α (TNF-α) in either tumor model." (PMID 36989357, 2023). "For molecular pathway regulation studies, NF-κB and TNF-a play a critical role in the link between inflammation and cancer through NF-κB’s ability to upregulate tumour-promoting cytokine and survival genes." (PMID 38067358, 2023). "Strikingly, we observed that overexpression of IFI35 promoted CD8+ T cells to secrete more IFNγ and TNFα in CT26 tumor." (PMID 37380972, 2023).